MYOCD (myocardin)
Diseases named in the same sentence as MYOCD in open-access papers (continued):
Sharing a sentence is not in itself a finding about the gene and the disease.
tumor (9 papers, 2010 to 2023). "Targeting MYOCD/SRF interaction with a specific inhibitor decreased the viability of a cell line derived from this tumor subgroup, which makes this pathway a potential therapeutic target." (PMID 36672483, 2023). "Conversely, MYOCD overexpression significantly inhibited tumor incidence of H460-Teton-MYOCD cell in DOX-treated nude mice." (PMID 33995678, 2021). "Conversely, SRF activation by over-expressed MRTF family members results in inhibited cell proliferation, and the SRF co activator Myocardin is a tumor suppressor whose expression is reduced in human tumors." (PMID 21573132, 2011). "Although MRTFs are required for experimental invasion and metastasis, the MAL homolog myocardin was recently described as a tumor suppressor." (PMID 20236507, 2010). "In contrast, while 3 of 6 sites (50%) of 500 inoculum and 2 of 6 sites (33%) of 50 inoculum in cohort of DOX treatment (knockdown of MYOCD expression) developed tumor, control-diet fed cohort developed at a significantly lower incidence (1 of 6 sites (17%) and 0 of 6 sites respectively)." (PMID 33995678, 2021). "Given its ability to negatively regulate TGF-β signaling, MYOCD inactivation may be a spontaneous event during tumor development, but not a drug selected event." (PMID 33995678, 2021).
cardiovascular diseases (8 papers, 2014 to 2025). "It is conceivable that Prmt1 ablation results in ER stress and unfolded protein responses through decreased myocardin expression associated with cardiovascular diseases." (PMID 34635781, 2021). "Using Myocardin/Stat3 (and analogs) to inhibit cardiomyocyte apoptosis holds promise as an effective therapeutic strategy for cardiovascular diseases." (PMID 29245928, 2017). "MYOCD is known to play a crucial role in cardiovascular disease." (PMID 41031220, 2025). "Considering myocardin plays a critical role in SMC contractility and contributes to the pathogenesis of cardiovascular disease, our findings further support a novel mechanism for high glucose in inhibiting MC contraction as well as a role in DN." (PMID 29152089, 2017).
cardiac disease (3 papers, 2012 to 2022). "We discuss the involvement of MYOCD, MRTF-A, and MRTF-B in the development of cardiac dysfunction and to what extent modulation of the expression of these factors in vivo can correlate with cardiac disease outcomes." (PMID 22666593, 2012).
heart (2 papers, 2013 to 2024). "For example, forced myocardin expression in human MSCs via adenoviral gene transfer promotes cardiomyogenic differentiation and transplantation efficiency in murine ischemic heart injury models." (PMID 38529014, 2024). "Down-regulation of miR-1, which occurs under different pathological conditions, and subsequent increase of myocardin activity might explain the up-regulation of smooth muscle marker genes in various diseases of the heart." (PMID 24068960, 2013).
renal disease (2 papers, 2017 to 2019). "The results showed the MYOCD is overexpressed in the DCM patients with renal disease compared to DCM alone cases." (PMID 30971740, 2019). "In the present study, we analyzed the cardiac-specific expression of MYOCD in DCM patients with renal disease and DCM alone cases." (PMID 30971740, 2019). "Our results suggest that mannitol increases the GFR by downregulating the expression of myocardin and the contractile gene SM α-actin, which may provide another potential mechanism for mannitol in therapy for renal disease." (PMID 29152089, 2017). "Here, we analyzed the expression levels of MYOCD in the DCM patients with and without renal diseases." (PMID 30971740, 2019).
genetic disorder (1 paper, 2019). "Despite these unique and important functions of Myocd in mice, no human genetic disorder associated with MYOCD variants has yet been defined." (PMID 31513549, 2019).
infection (1 paper, 2025). The state of being infected such as from the introduction of a foreign agent such as serum, vaccine, antigenic substance or organism. "Here, infection with Ad-PARP1 suppressed myocardin or myocardin–SRF overexpression-induced luciferase activities driven by WT-SM22α, indicating that overexpression of PARP1 suppressed myocardin–SRF-dependent promoter activation." (PMID 40744995, 2025). "Consistently, infection with Ad-PARP1 also suppressed myocardin or myocardin–SRF overexpression-induced 6×CArG-drove luciferase activity." (PMID 40744995, 2025). "In line with this, ChIP–qPCR showed that infection with shPARP1 or treatment with PARP inhibitor (3AB or PJ34) increased recruitment of myocardin–SRF to SM22α promoters." (PMID 40744995, 2025). "Consistently, infection with Ad-myocardin versus Ad-Null suppressed luciferase activity driven by 6×AP1." (PMID 40744995, 2025). "This was confirmed by the fact that infection with Ad-PARP1 reversed myocardin overexpression-induced reduction in luciferase activities driven by WT-CyclinD1, WT-MMP9 promoter and 6×AP1." (PMID 40744995, 2025). "Infection of rVSMCs with Ad-myocardin shRNA versus scramble shRNA resulted in 5,271 DEGs (FDR <0.05), among which 2,903 genes were upregulated and 2,368 genes were downregulated." (PMID 40744995, 2025). "In PDGF-BB-treated rVSMCs, infection with Ad-myocardin shRNA abolished PJ34- or shPARP1-induced suppression of EdU incorporation and wound closure." (PMID 40744995, 2025). "The heat map shows that Ad-myocardin shRNA infection resulted in a transcriptome pattern nearly opposite that of scramble controls." (PMID 40744995, 2025). "Specifically, heat maps showed that infection with Ad-myocardin shRNA resulted in opposite transcript patterns of genes involved in contraction, proliferation and migration to scramble controls, indicating a critical role for myocardin in PJ34-induced transcript alteration of these genes." (PMID 40744995, 2025). "In support of this, infection with Ad-PARP1 decreased myocardin–c-Jun coprecipitates, but infection with Ad- mut-PARP1 did not." (PMID 40744995, 2025).
inflammation (1 paper, 2019). Aberrant reaction of the microcirculation characterized by movement of fluid and leukocytes from the blood into extravascular tissues. "Therefore, this and other studies present myocardin as a molecular therapeutic target in vascular inflammation." (PMID 31717401, 2019).
MYOCD also shares sentences with these, for which no sentence is quoted: acute myocardial infarction (2 papers); aneurysmal disease (2); breast carcinoma (2); cerebral amyloid angiopathy (2); megakaryoblastic leukemia (2); acute megakaryoblastic leukemia (1); atrial fibrillation (1); bladder cancer (1); cardiovascular disease hypertension (1); ciliopathies (1); colorectal cancer (1); congenital lower urinary tract obstruction (1); cystic kidney disease (1); dissection (1); esophageal cancer (1); frontometaphyseal dysplasia (1); gastric adenocarcinoma (1); glioblastoma (1); glioma (1); hematological disease (1); hydronephrosis (1); Hydroureter (1); Hyperglycemia (1); liver cancer (1); metabolic disorder (1); mood disorder (1); muscular atrophy (1); Myocardial fibrosis (1); neurodevelopmental disorder (1); ovarian carcinoma (1).
A further 4 diseases each share a sentence with MYOCD in 1 paper.